CD4 (CD4 molecule)
Diseases named in the same sentence as CD4 in open-access papers (continued):
Sharing a sentence is not in itself a finding about the gene and the disease.
tumor (continued). "Although both AAA-CD4+ and auto-CD4+ T-cell therapies induced NK cell infiltration in the tumor at 4 h, this effect was maintained only in the AAA-CD4+ group at 24 h." (PMID 34625113, 2021). "The tumor-infiltrating CD4+ cells in the combination group also showed higher expression of the costimulatory marker GITR and a greater proportion of PD-1+GrzB+ cells (p<0.0001 and p=0.0007, respectively)." (PMID 34281988, 2021). "Using experimental in vitro models, we and others demonstrated that tumor cells can trigger in human CD4+ and CD8+ T lymphocytes the acquisition of suppressive functions and phenotypic alterations that resembled those found in senescent cells." (PMID 34386013, 2021). "In this study, IP (intraperitoneal) injection of 40 mg/kg resveratrol led to downregulation of the immunosuppressive cytokine TGF-beta, and inhibition of the CD4+ CD25+ cell population in the spleens of B16F10 tumor-bearing mice." (PMID 33802331, 2021). "A cognate interaction between tumor antigen-specific CD4+ Th1 cells and macrophages can shift the intratumoral M1/M2 ratio toward M1." (PMID 34681680, 2021). "We observed significant correlations between the expression levels of the core DEGs SATB-2, ORP-1, MYB, and CDX-2 and tumor immune cell infiltration represented by the expression of B cell, CD4+ T cell, CD8+ T cell, and macrophage markers in TCGA." (PMID 33632198, 2021). "Next, 105/well CD8 or CD4 T cells and 5×104/well of tumor cells were each plated in triplicate wells of 96-well plates and incubated at 37°C for 24 hours." (PMID 33637599, 2021). "In contrast, much lower percentages of CD103+ cells among FoxP3+CD4+ Treg were observed in B16F10E-KO tumours than in B16F10E." (PMID 34471106, 2021). "The percentage of Tregs in tumor infiltrating CD4+ T cells was 34.1%, which was increased by treatment with BLM to 50.4% and decreased by treatment with CY to 14.8%." (PMID 34378880, 2021). "Growing evidence has indicated that Tumor-infiltrating B (TIL-B) cells contribute to the prognostic effect of tumors by inducing CD4+ T cells and CD8+ T cells, which help to regulate tumor invasion and metastasis." (PMID 34976013, 2021). "Upon combination with an anti-PD-1 antibody, the anti-tumor effects of romidepsin were enhanced and the influence on CD4+ and CD8+ T cells was partially reversed." (PMID 32632663, 2021). "Remarkably, the VP1 in a combination of both adjuvants caused more cytokine secretions and ultimately tumor regression, which was associated with reduced frequency of TGF-β-expressing CD4+ Treg cells." (PMID 34611173, 2021). "Recruitment of CD4+Foxp3+ Tregs to the tumor bed is an important mechanism by which tumors evade immune surveillance." (PMID 34676831, 2021). "Tfh cells (CD4+PD1+CXCR5+) can exhibit a tumor-supporting role in human B cell malignancies, foremost in FL and CLL18." (PMID 33431832, 2021). "A flow cytometry analysis showed that the proportion of CD4+ T cells in the spleen was increased after cryo-thermal therapy combined with sEV injection compared to that in the tumor-bearing group." (PMID 34681680, 2021). "In the past decade, it has become clear that CD4+ T cells play a multifaceted role and are crucial for generating effective anti-tumor immunity." (PMID 34012451, 2021). "CD4+ T lymphocytes took on activities in the immune response against tumor by secreting cytokines and activating CD8+ T lymphocytes." (PMID 34566989, 2021). "Treatment also promotes an immunosuppressive tumour microenvironment through CD4+ Treg and FoxP3+ NKT cells." (PMID 34359633, 2021). "With respect to FOXP3 expression, we observed an increased methylation in the gene body, after the promotor region, and increased RNA levels in CD4+ T cells from tumor." (PMID 34012510, 2021).
tumor (continued). "Immune cell infiltration was also detected in specific areas of the tumor tissue, showing infiltration of CD4+ T cells and CD68+ cells but rarely CD8+ T or B cells." (PMID 34070094, 2021). "In order to confirm our findings, we quantified the infiltration level of CD4+GzmBCT+ T cells was quantified and the patients were divided into two groups based on the median levels of CD4+ GzmB+ T cells in the central tumor." (PMID 34631551, 2021). "Activated DCs migrate to the draining LNs where they activate tumor antigen-specific CD4+ Th2 cells to exert tumor-promoting effector functions." (PMID 34305902, 2021). "Tregs are a subset of CD4+T cells, which maintain peripheral tolerance and suppress anti-tumor immune responses." (PMID 33968044, 2021). "Few data further shed light on TNFAIP8 in immune response processes, including an increasing trend of TNFAIP8 mRNA levels in tumor-infiltrating CD4+ CD8+ T cells and the tendency of CD4+ T cells immune function modulation both in mice and humans." (PMID 34925463, 2021). "The proportions of tumor-infiltrating CD4+ T cells, CD8+ T cells, neutrophils, macrophages, and dendritic cells were closely related to our prognostic risk score (p < 0.05)." (PMID 33747044, 2021). "The constitutive HLA class II expression on tumor cells results in their recognition by tumor-antigen-specific CD4+ T cells, generating a Th1 response." (PMID 34359808, 2021). "The evaluation of tumor-infiltrated CD4+CD25+Foxp3+ regulatory T cells designated that treatment of mice with TEXomiR significantly (P = 0.032) decreases the tumor-infiltrated CD4+CD25+Foxp3+ T cells in the TEXomiR group compared with the PBS group." (PMID 33987190, 2021). "As well as immune checkpoint inhibitors to enhance cytotoxic CD8+ TILs activity in the tumor microenvironment, tumor control requires CD4+ T helper cells to provide activating cytokines to CTLs." (PMID 34900690, 2021). "It has been shown that epigenetic modulators can improve the efficacy of adoptive CD4+ T cell therapies by increasing MHC expression on tumor cells." (PMID 34262562, 2021). "Some studies identified the immunoscore of tumor tissue and serum interleukin-6 (IL-6), IL-11 or CD4+/CD8+ T cell also reflecting the immunoinflammatory status, but it is hard to be used in clinical practice due to the high cost and inconvenience." (PMID 34195071, 2021). "In contrast, some pathway activities related to immune depletion were significantly activated in CD4+ naive T cells (clusters 0 and 2) located in the core of the tumor; these pathways included FGFR signaling, lipid fatty acid synthesis, and MAPK signaling." (PMID 34513820, 2021). "Immune cells, including CD4+ and CD8+ T cells, regulatory T cells (Tregs), tumor-associated macrophages (TAMs), and myeloid-derived suppressor cells (MDSCs) are the main immune cells frequently infiltrating tumors, including HNSCC." (PMID 33804419, 2021). "The results showed that both of them were negatively correlated with tumor purity, and were significantly correlated with T cell promoter helper, T cell CD4+, Myoid derived suppressor cells, Neutrophil, Macrophages and B cell." (PMID 34123826, 2021). "Being TSAs that absent in normal cells, viral antigens are endowed with a powerful capability to induce cellular immune response mediated by CD4+ and CD8+ T lymphocytes to eliminate virus-associated tumor cells." (PMID 33503926, 2021). "Simultaneously, the infiltration levels of tumor-repressing leukocytes, including NK, B, Tfh, CD4+ T cells, and Th17, were negatively correlated with PBK mRNA expression." (PMID 33431797, 2021). "Consistently, C34 + US induced higher differentiation of CD4+ T cells into the memory phenotypes (CD44hiCD4+), indicating the potential of generating a long-lasting immune memory to prevent tumor relapse." (PMID 34669472, 2021).
tumor (continued). "We observed that LUAD with EGFR mutated have less infiltration of anti-tumor immune cells, including CD8+ T cells, activated CD4+ T cells and M1 macrophages, and increased M2 macrophages infiltration." (PMID 34178613, 2021). "Co-inhibitory CTLA-4 competes with co-stimulatory CD28 to bind to CD80 or CD86 on the surface of APCs to alleviate the anti-tumor immunity of tumor infiltrated T lymphocytes (TILs), such as CD4+T, CD8+T cells and regulatory T cells (Tregs)." (PMID 34858835, 2021). "The B cell-specific production of IL-35 promoted the expansion of Treg cells and blocked the anti-tumor activity of effector CD4+ T cells." (PMID 33418929, 2021). "Tumor-infiltrating lymphocytes (TILs), the greatest enforcers of anti-tumor immunity, are present in BCBMs and primarily consist of helper CD4+ and cytotoxic CD8+ T cells." (PMID 34716900, 2021). "A comprehensive analysis of the immune microenvironment revealed an expected increase in the ratio of CD4/CD8 tumor-infiltrating T cells, with the frequency of CD4+ cells more than doubling in the Batf3–/– mice." (PMID 34283809, 2021). "The drug increased CD8/CD4 ratio both in LNs and lung tissues and significantly reduced tumor burden with respect to untreated animals." (PMID 33854047, 2021). "A discussion on the role of H. pylori is presented, followed by a brief review on the effects of CD4+ T-cell differentiation in the GC tumour microenvironment (TME) on cytokine levels." (PMID 34944729, 2021). "Further analysis demonstrated that a majority of immune cells exhibit a varying infiltration pattern, while activated CD4 T cells are an intriguing exception and were consistently decreased in tumor samples with a high luminal A-like phenotype." (PMID 34869761, 2021). "A negative correlation was observed between TNFRSF11B expression levels and the infiltration of activated memory CD4+ T cells into the tumor microenvironment using this dataset." (PMID 34938284, 2021). "In melanoma, tumor sEVs also induce the mitochondrial apoptotic pathway in CD4+ T-cells, and this is mediated by transfer of miRNA cargos miR-690, miR-677 as well as miR-29b." (PMID 34503190, 2021). "The capacity of daily CR to decrease the frequency of Foxp3+CD8+, Foxp3+CD4+, and MDSCs is consistent with protection from the metastatic potential of tumor cells." (PMID 34707136, 2021). "The correlation of the biomarkers with the tumour microenvironment suggested that the high riskScore was positively related to the enrichment of resting natural killer cells and activated memory CD4 + T cells." (PMID 34876138, 2021). "The infiltration proportion of anti-tumor immune cells, including activated CD4+ T cell, activated CD8+ T cell and nature killer (NK) cell is higher in the cGAS-STING high cluster." (PMID 34625078, 2021). "Tumour immune infiltrates were primarily comprised CD11b+ myeloid cells, with a paucity of CD4+ and CD8+ T cells, as previously reported." (PMID 34784792, 2021). "All the gene signatures other than those of PRDX6 and HTATIP2 were correlated with tumour purity and B cell, CD4+ T cell, CD8+ T cell, macrophage, neutrophil and dendritic cell levels." (PMID 34760691, 2021). "In CBL, CD4+ or CD8+ T cells treated with phosphate buffer saline were more active than those treated with tumor-derived IgG or intravenous Ig." (PMID 34226529, 2021). "Similar findings on elevated glucose uptake and mitochondrial mass were detected in the tumor-infiltrating CD8+ or CD4+ T-cells with the T+H combination therapy (p < 0.05)." (PMID 33391535, 2021). "Transposons coding for oncogenic ras linked to potent CD4 and CD8 T cell epitopes was used to transform hepatocytes into nascent tumors with tailored tumor immunogenicity." (PMID 34209393, 2021). "Immunohistochemistry was performed to analyze the proportion of CD8+T cells and CD4+T cells in the tumor." (PMID 34422050, 2021).
tumor (continued). "PD-1H protein was predominantly expressed in CD68+ tumor-associated macrophages and expressed at low levels in CD4+ T cells and CD8+ T cells in ESCC tumor tissues." (PMID 34950702, 2021). "Both CD4+ and CD8+ TILs proportions in spontaneous and transplanted UPS tumours were low: CD4+ 0.8% +/- 0.2 and 1.8% +/- 0.4, respectively; CD8+ 1.1% +/- 0.4 and 3.7% +/- 2.0, respectively." (PMID 34242269, 2021). "Meanwhile, CD4+ Treg cell-mediated anti-tumor immunosuppression is the main mechanism of tumor immune evasion and immunotherapy resistance." (PMID 34712660, 2021). "The KV regimen induces a Th1 dominant Thelper cell profile in the TC-1 tumor model, with higher proliferative capacity and reduced CD4+ Treg frequencies and proliferation." (PMID 34885215, 2021). "Limited dilution gave up to 50 T-cell clones, all CD4+, with low efficiency (0.02%), probably reflecting a slight expanding attitude of peri-tumor T lymphocytes in in-vitro culture conditions." (PMID 34944746, 2021). "According to this model, in TME was observed abundant PD-L1+TAMs and PD-1+ CD4 T cells, that were in contact with PD-L1+ tumor cells." (PMID 34682791, 2021). "Treg cells, a subset of CD4+ T cells characterized by its ability to dampen immune responses, are attracted to the tumor stroma via chemokine receptors CCR4, CCR5, CCR6, and CCR10." (PMID 34771482, 2021). "Consistent with this, we observed that an optimized local anti-tumour CD8 T cell immunity correlates with a decreased frequency of CD103+CD4+ Treg cells in anti-PD-1-treated-αV-knockout tumours." (PMID 34471106, 2021). "As a result, 24 h after intratumoral injection, mice that received AAA-CD4+ T-cell therapy had significantly more host-type NK cells in the tumor than mice that received auto-CD4+ T cells and PBS-treated control mice." (PMID 34625113, 2021). "Antitumoral cytotoxic cells such as CD8+ and CD4+ T cells, Th1/2 cells, as well as tumor promoting regulatory cells and macrophages were correlated with the APOBEC, exhaustion and dormancy programs." (PMID 34307377, 2021). "Overall, the results show that the presence of polyfunctional, tumor reactive CD4+ T cells can be a desirable prognostic biomarker for survival." (PMID 33669271, 2021). "In fact, on mice not treated, T cells were not present on the pulmonary tissue around the tumor and on the tumor infiltration, whereas on anti-VEGF treated mice CD4+ T cells infiltrated tumor, with CD8+ at tumor margin." (PMID 36046087, 2021). "This revealed some interesting relationships, such as the consistent coexistence of Type 1 macrophages with DCs and to a lesser extent CD4+ T cells in particular in the interface domain, while they were being rarely found in close contact with tumour cells." (PMID 34625563, 2021). "B cells produce tumour reactive antibodies that facilitate tumour killing by NK and CD4+ CD8+ T cells and phagocytosis by macrophages." (PMID 33573141, 2021). "Our results showed differentiation paths from normal‐specific natural killer cells to tumor‐derived CD8+/CTL T cells, tumor‐derived CD4+ T cells, and tumor‐derived regulatory T cells." (PMID 33783985, 2021). "During tumor immunity, CD4+ T cells and CD8+ T cells exhaustion will promote tumorigenesis and development, in this process PD-1 is the major inhibitory receptor." (PMID 33306121, 2021). "ACT is the transfer of sensitized lymphocytes (such as TILs, CD8+ cells, CD4+ helper cells, and NKs, etc.)which have been manipulated and amplified in vitro to cancer patients to obtain anti-tumor immunity." (PMID 34150736, 2021). "In this study, we found that CD4+ naive T cells located at the core of the tumor had higher expression levels of immune checkpoint molecules than those in other locations of the tumor." (PMID 34513820, 2021).
tumor (continued). "The results suggested that the tumor infiltrating leukocytes including macrophages M0, monocytes, NK cell activation, T cell CD4+ naive and T cell regulatory (Tregs) were significantly different in number between the high-risk and low-risk groups." (PMID 35118063, 2021). "Many previous studies have indicated that CD8+ T cells, CD4+ memory activated T cells, NK cells, T-follicular helper cells, and activated DCs are protective factors in tumor patients." (PMID 33854974, 2021). "Th1 polarized CD4+ T-cells orchestrate and maintain anti-tumor immune response by directly secreting effector cytokine such as IFNγ and TNFα and also by activating and supporting cytotoxic CD8+ T-cells." (PMID 34012510, 2021). "miR155 is required for optimal effector CD8+ T cell accumulation, memory cell differentiation and anti-tumor activity, as well as CD4+ T cell functions, including activation, function, apoptosis and differentiation." (PMID 35046962, 2021). "Some data suggest that Th17 CD4+ T cells have superior anti-tumor function and improved persistence as compared to Th1 cells in adoptive cell therapy settings." (PMID 34012443, 2021). "The role of CD4 T cells as the “helpers” required for the appropriate stimulation of tumor-reactive CD8 T cells, has always been acknowledged." (PMID 34201655, 2021). "Compared with normal mice, tumor-bearing mice showed distinctly reduced CD4+ T cell subset and enhanced CD8+ T cell subset frequencies in both spleens and blood." (PMID 33537094, 2021). "We observed that the proportion of Treg cells among CD4+ T cells in the tumours was much higher than that in the PBMC." (PMID 33531485, 2021). "We next examined the ‘cool’ 4T1 tumor-infiltrating CD4+ and CD8+ T cells by performing flow cytometry on bulk tumors." (PMID 33602696, 2021). "As a result, AAA-CD4+ T cells induced approximately 4-fold more host CD8+ TEM cells in the tumor 24 h after injection, compared to auto-CD4+ T cells." (PMID 34625113, 2021). "Similar to the human CD177+ TI Treg cells, we found that Treg cells from tumor-bearing WT mice exhibited a stronger suppressive capacity against both CD4+ and CD8+ T cells compared to Treg cells from tumor-bearing Cd177-KO mice." (PMID 34599187, 2021). "A decreased cellular immunity is characteristic of GBM, to which an increased proportion of Tregs among CD4+ TIL (tumour-infiltrating lymphocytes) has been shown to contribute both in patients and in pre-clinical models." (PMID 34675201, 2021). "Compared to the control mice challenged with LL/2-tdTomato/Luc tumor cells, depletion of CD4+ T cells, CD8+ T cells, or NK cells resulted in elevated tumor growth comparable to LL/2 cell challenge group and led to significant reduction in survival of the mice." (PMID 34411144, 2021). "Flow cytometry of PDV and PDVC57 tumors injected into B6 mice showed that PDVC57 tumors contained more tumor-associated macrophages (TAM), fewer tumor-infiltrating dendritic cells, and fewer tumor-infiltrating CD4+ and CD8+ T cells." (PMID 34031449, 2021). "CAFs induce and recruit regulatory T cells (Tregs) to repress antitumor immune responses and support tumor progression by the induction of CD4+ helper T (TH) lymphocytes to strengthen pro-tumorigenic TH2 and TH17 phenotypes." (PMID 33806802, 2021). "Regulatory CD4+ T cells (Treg) prevent tumor clearance by conventional T cells (Tconv) comprising a major obstacle of cancer immune-surveillance." (PMID 33602930, 2021). "The effector T cells—CD8+ cytotoxic T lymphocytes (CTLs) and CD4+ T cells—in a Th1 response migrate back to the nascent tumor TME." (PMID 34950576, 2021). "In turn, CXCL13 overexpression seems to attract effector/cytotoxic PD-1+ CD4+ T cells to tumor cells, which promotes CD4+ T cell-mediated tumor cell inhibition and killing." (PMID 34795254, 2021).